PYCR1 (pyrroline-5-carboxylate reductase 1)
Diseases named in the same sentence as PYCR1 in open-access papers (continued):
Sharing a sentence is not in itself a finding about the gene and the disease.
tumor (continued). "MS-based proteomic profiling of 113 FFPE tumor samples identified proline biosynthesis enzymes (PYCR1 and ALDH18A1) as markers of NAC resistance." (PMID 40790759, 2025). "This dual role in coordinating tumor metabolism and immunomodulation has propelled PYCR1 into the forefront of translational oncology research, though mechanistic details of its tumorigenic circuitry and therapeutic vulnerability remain to be fully deciphered." (PMID 40430095, 2025). "The PYCR1-overexpressing A549 cells treated with EGF or TLR agonists exhibited significantly larger tumor spheroids compared with mock-transfected cells." (PMID 41254241, 2025). "Stable FTO promotes BLCA cell proliferation and migration in vitro and tumor development in vivo by decreasing the m6A methylation of pyrrolidine 5‐carboxylate reductase 1 (PYCR1) and lengthening the mRNA half‐life of PYCR1." (PMID 40919129, 2025). "Genetic or pharmacologic inhibition of PYCR1 results in reduced tumor growth and increased cell death in preclinical models, underscoring its potential as a therapeutic target." (PMID 41200384, 2025). "This integrated multi-modal analysis establishes PYCR1 as a pivotal regulator of ccRCC pathophysiology, orchestrating tumor cell survival, mitotic progression, and metastatic dissemination through molecular mechanisms warranting further exploration." (PMID 40430095, 2025). "We further examined the role of PYCR1 in 3D tumor spheroid formation under EGF and TLR agonist treatment." (PMID 41254241, 2025). "Second, mitochondrial oxidative stress induced by Lon-PYCR1 has been reported to maintain an immunosuppressive tumor microenvironment that promotes cancer progression and metastasis." (PMID 41254241, 2025). "Future studies will delineate PYCR1’s downstream targets and validate its in vivo tumor-promoting effects." (PMID 40430095, 2025). "In contrast, kindlin‐2 knockdown reduces PYCR1 levels, leading to suppressed tumor growth and improved survival outcomes." (PMID 41200384, 2025). "Our study reveals the expression pattern and tumour‐promoting role of PYCR1 in LC and identifies the downstream target IRS1 through which PYCR1 promotes LC progression." (PMID 39422696, 2024). "Our findings identify PYCR1 as a pivotal regulator of LC progression that influences tumour cell metabolism and gene expression." (PMID 39422696, 2024). "Pyrroline‐5‐carboxylate reductase 1 (PYCR1) is a key enzyme for proline synthesis that is highly expressed and plays a vital role in a variety of tumours." (PMID 39422696, 2024). "The expression of PYCR1 was confirmed by RT-qPCR in SNSCC tissues, and its high expression was associated with poor overall survival, indicating PYCR1 as a potential tumor-associated biomarker to predict the prognosis of SNSCC." (PMID 39768999, 2024). "We noticed the activation of the proline cycle (↑ PEPD, POX/PRODH and PYCR1) to indicate constant remodeling (synthesis and degradation) of matrix collagen, which in turn can contribute to tumor heterogeneity." (PMID 38397798, 2024). "Reducing PYCR1 levels in CAFs is sufficient to reduce tumor collagen production, tumor growth and metastatic spread in vivo, and cancer cell proliferation in vitro." (PMID 39335478, 2024). "The Western blot results revealed that the changes in the expression of cell cycle‐related proteins, apoptosis‐related proteins and tumour metastasis‐related proteins were abolished after IRS1 was overexpressed in PYCR1‐knockout or PYCR1‐inhibited LC cells." (PMID 39422696, 2024). "This explanation is in keeping with the known appetite for glutamate exhibited by GG4 cells, which, for this reason, is dubbed a “glutamate-addicted tumor” since glutamate is the main fuel for PYCR1 to restitute NAD+." (PMID 38275897, 2024). "The percentage of cells with strong positive staining was significantly higher for tumor tissue when treated with PYCR1, PEPD, and MMP-9 antibodies (p < 0.0001) and lower when treated with POX/PRODH (p < 0.0001)." (PMID 38275897, 2024).
tumor (continued). "Lowering the expression of PYCR1 in CAFs has been shown to effectively decrease collagen production within tumours, inhibit tumour growth and limit metastasis." (PMID 39422696, 2024). "The protein levels of MELK and PYCR1 were upregulated in tumor tissues compared with adjacent tissues." (PMID 37340189, 2023). "In vivo, NOD/SCID mice inoculated with shPYCR1 cells evidently formed smaller tumor masses than the mice injected with shNC cells, indicating that PYCR1 is essential for tumor growth." (PMID 37845207, 2023). "As expected, the level of PYCR1 pY135 and IGF1R phosphorylation were significantly correlated; the signals of PYCR1 pY135 also exhibited a positive relationship with that of HIF-1α in distinct tumor regions." (PMID 37777542, 2023). "In vivo and in vitro, reducing PYCR1 levels in CAFs reduces tumor collagen production, tumor growth, and metastatic spread." (PMID 37496657, 2023). "Increased expression of the proline synthesis pathway enzyme pyrroline-5-carboxylate reductase 1 (PYCR1) has been noted in several tumor types and is a marker of poor prognosis." (PMID 37672588, 2023). "Meanwhile, the level of PYCR1 pY135 was shown to correlate with HIF-1α levels in mice tumor tissues." (PMID 37777542, 2023). "On the one hand, both ASS1, which is the key enzyme in arginine metabolism, and PYCR1, which is responsible for proline synthesis, were highly expressed in both tumour tissues and cell lines under limited oxygen conditions." (PMID 36978187, 2023). "In the clinic, the level of PYCR1-cGMP-PKG axis is enriched in tumor specimens from TNBC patients and confers poor prognosis." (PMID 37845207, 2023). "In current study, psychological stress elevates mRNA and protein expression of PYCR1 and increases proline levels during tumor development." (PMID 37845207, 2023). "Increased matrix stiffness is intrinsically linked to up-regulation of proline synthesis via the kindlin-2 and PYCR1 complex, which in turn promotes collagen synthesis, cell survival and tumor progression." (PMID 37752116, 2023). "Immunohistochemistry (IHC) indicated the level of PYCR1 was largely elevated in tumor tissues compared with the adjacent normal tissues." (PMID 37777542, 2023). "The results showed that suppression of proline biosynthesis by silencing PYCR1 significantly reversed psychological stress-induced tumor progression." (PMID 37845207, 2023). "It was shown that either PYCR1 pY135 or IGF1R phosphorylation levels were increased in tumor tissues compared with the adjacent normal tissues." (PMID 37777542, 2023). "Consistent with previous study in other cancer types, our data show that silencing of PYCR1 decreases proline level to inhibit proliferation and induce apoptosis in TNBC cells, these phenotypes also contribute to PYCR1-mediated tumor growth." (PMID 37845207, 2023). "Consistent with the effect of the IGF1R inhibitor linsitinib, shASS1/PYCR1 demonstrated a synergistic effect on tumour-proliferation inhibition with DDP in vitro and in vivo." (PMID 36978187, 2023). "Since proline has a major impact on energy metabolism, glycolysis, the redox state, apoptosis and proliferation of tumor cells, PYCR1 has been suggested as a therapeutic candidate target in many cancers to which we now can add aggressive TETs." (PMID 35326714, 2022). "PYCR1 is a particularly promising metabolic vulnerability, as it is among the most overexpressed genes across tumor types." (PMID 36324182, 2022). "Many studies have demonstrated the overexpression of PYCR1 in several kinds of tumor tissues and the importance of PYCR1 in tumorigenesis and cancer progression 20-23,27." (PMID 35371311, 2022). "Our results revealed that PYCR1 expression was higher in tumor tissues compared with that in the adjacent normal tissues." (PMID 35371311, 2022). "These are particularly encouraging findings that PYCR1 plays a vital role in tumor initiation and progression 33-35." (PMID 35371311, 2022).
tumor (continued). "We found that the extent of hypoxia increased significantly across the tumor in response to knockdown of PYCR1." (PMID 35108535, 2022). "Meanwhile, IHC scores of PYCR1 in tumor tissues were significantly greater than in the paired normal tissues (Tumor vs Normal = 3.0 ± 2.1 vs 1.7 ± 1.9, P <0.001)." (PMID 35371311, 2022). "Targeting PYCR1 in CAFs reduced tumour collagen deposition in vitro and in vivo and was sufficient to reduce tumour growth and metastasis." (PMID 36324182, 2022). "We therefore propose that inhibition of PYCR1 is a viable target for killing cancer cells in hypoxic tumor regions, which are refractory to many conventional treatment approaches." (PMID 35108535, 2022). "The study found that the expression of PYCR1 in 89 tumor tissues was significantly higher than that in the paired adjacent normal tissues." (PMID 35371311, 2022). "This is an important finding, because PYCR1 is among the top 20 metabolic genes overexpressed across cancer types, and proline synthesis has been proposed as a tumour-specific vulnerability." (PMID 35760868, 2022). "And in vivo, PYCR1 interference also significantly inhibited tumor growth both in the tumor volume and weight." (PMID 35371311, 2022). "Fifth, the current study found that inhibition of PYCR1 can also enhance the effect of other anti-tumor drugs." (PMID 36119513, 2022). "Reducing PYCR1 levels in CAFs is sufficient to reduce tumour collagen production, tumour growth and metastatic spread in vivo and cancer cell proliferation in vitro." (PMID 35760868, 2022). "During recent years, PYCR1 has attracted increasing interest because its upregulation has been found involved in tumour growth and metastatic progression of several types of cancers." (PMID 34107832, 2021). "Further, the results of the HCC xenograft mouse study indicated that silencing PYCR1 significantly inhibited the tumor growth." (PMID 34239351, 2021). "A meta-analysis of metabolic enzyme expression across diverse tumor types identified pyrroline-5-carboxylate reductase (PYCR1), the principal enzyme in proline biosynthesis, as one of the most commonly overexpressed genes in tumors." (PMID 34650434, 2021). "The expression level of PYCR1 was negatively correlated with tumor purity and has significant positive correlations with dendritic cells, but not with the infiltration levels of CD8+ T cells, CD4+ T cells, B cells, macrophages, and neutrophil." (PMID 34868460, 2021). "The authors also found that ccRCC upregulated PYCR1 in order to compensate for this proline deficit and was a targetable vulnerability in these tumours." (PMID 34939929, 2021). "This study showed that hsa-miR-150-5p levels were downregulated in the NPC tissue samples and cells and were negatively correlated with the PYCR1 levels in the NPC tumor tissue samples." (PMID 34696668, 2021). "In vivo kindlin-2 ablation strongly reduced PYCR1 and proline level, fibrosis, tumor growth and mortality rate." (PMID 34769188, 2021). "It was found that in the kidney cancer cells, depleting Asn by ASNase activates the expression of PYCR1 for tumor growth, which is a key enzyme in Pro production." (PMID 33477430, 2021). "Compared with the control mice, those with downregulated PYCR1 expression exhibited a delayed onset of tumor growth and a smaller tumor volume after 4 weeks of observation." (PMID 34239351, 2021). "In vivo Kindlin-2 ablation strongly reduces PYCR1 and Proline levels, fibrosis, tumor growth and mortality rate." (PMID 32500033, 2020). "The requirement of PYCR1 activity for tumor growth, further support the idea that Proline availability controls cancer progression." (PMID 32500033, 2020). "We recently found that a fraction of kindlin-2, a focal adhesion protein, is translocated into mitochondria where it forms a complex with PYCR1, which prevents PYCR1 degradation and thereby promotes proline synthesis, tumor fibrosis, and growth." (PMID 33004813, 2020).
tumor (continued). "Our results identify a signaling axis consisting of PINCH-1, DRP1 and PYCR1 that regulates mitochondrial dynamics and proline synthesis, and suggest an attractive strategy for alleviation of tumor growth." (PMID 33004813, 2020). "PYCR1 significance remained even after correction for potential confounding factors, including tumor size, grade, and M&P score." (PMID 32960509, 2020). "PYCR1 knockout significantly reduced tumor burden and increased drug sensitivity of orthotopically injected ER‐positive tumor in vivo, thus emphasizing the role of PYCR1 in resistance to chemotherapy." (PMID 32960509, 2020). "But also as a protein related to amino acid metabolism, PYCR1 was highly expressed to maintain the redox balance of tumor cells and prevent apoptosis by synthesizing proline." (PMID 33200655, 2020). "In agreement with our in vitro results, PYCR1‐KO tumors induced a slight but significant reduction in tumor size in vivo." (PMID 32960509, 2020). "In clinically, we analyzed PYCR1 protein and mRNA levels from 140 pairs of tumor and adjacent normal liver tissues of HCC patients, and found that PYCR1 levels were significantly up-regulated in HCC tumor tissues than adjacent normal liver tissues." (PMID 31619254, 2019). "Protein and mRNA expression levels of PYCR1 in 140 pairs of tumor and adjacent normal liver tissues of HCC patients were analyzed by immunohistochemistry and quantitative real-time polymerase chain reaction (qRT-PCR)." (PMID 31619254, 2019). "Our data revealed that PYCR1 levels were higher expressed in tumor tissues than adjacent normal ones, and IHC scores were statistically significant higher in tumor tissues (P < 0.001)." (PMID 31619254, 2019). "PYCR1 is one of the most commonly over-expressed metabolic genes in 1981 tumor samples spanning 19 types of cancers." (PMID 31143549, 2019). "The expression level of PYCR1 in tumor tissues and cells was assessed, and prognosis relying on its expression level also was analyzed using statistical methods." (PMID 31428683, 2019). "PYCR1 levels were significantly up-regulated in HCC tumor tissues than adjacent normal liver tissues in both protein and mRNA levels (P < 0.01)." (PMID 31619254, 2019). "In order to determine how PYCR1 regulates the physiological processes of tumor cells, we first examined the effect of silencing PYCR1 on the Akt/mTOR pathway." (PMID 31428683, 2019). "Importantly, mitochondrial oxidative stress by Lon-PYCR1 maintains an immunosuppressive tumor microenvironment that promotes cancer progression and metastasis." (PMID 41254241, 2025). "Additionally, PINCH‐1 has been shown to strengthen the interaction between kindlin‐2 and PYCR1, further promoting proline production and tumor progression." (PMID 41200384, 2025). "Importantly, it has been reported that mitochondrial oxidative stress mediated by Lon-PYCR1 maintains an immunosuppressive tumor microenvironment and promotes cancer progression through ROS-dependent p38 and NF-κB signaling." (PMID 41254241, 2025). "CBP (CREB‐binding protein) acetylates PYCR1, leading to suppression of tumor cell growth." (PMID 41200384, 2025). "Furthermore, a PYCR1 chemical inhibitor, PYCR1-IN-1, significantly suppressed the 3D tumor spheroid formation driven by both TLR and EGFR signaling." (PMID 41254241, 2025). "The treatment with PYCR1-IN-1 markedly reduced the cell proliferation and the tumor spheroid size induced by the EGFR or TLR agonist in H1975 and HCC827 cells compared with cells treated with EGF or TLR agonists alone (vehicle versus PYCR1-IN-1 in H1975, vehicle versus PYCR1-IN-1 in HCC827)." (PMID 41254241, 2025). "Importantly, treatment with 10 μM PYCR1-IN-1 significantly reduced the size of EGFR- or TLR-induced tumor spheroids in H1299, H460, A549, H358 cells compared with cells treated with EGF or TLR agonists alone." (PMID 41254241, 2025). "PYCR1-driven proline synthesis supports redox balance and tumor growth." (PMID 40863132, 2025).
tumor (continued). "It is confirmed that PYCR1 is significantly overexpressed in SNSCC, suggesting that it plays an important role in tumorigenesis and could be a promising tumor-associated marker in SNSCC." (PMID 39768999, 2024). "Overall findings indicate that PYCR1 plays an important role in tumor initiation and progression." (PMID 39768999, 2024). "Tumor PYCR1 expression was 66% higher than in the control (p = 0.0099)." (PMID 38275897, 2024). "Our results indicate that SUIT-2 cells subjected to FTH1 silencing exhibit a significant decrease in PYCR1 mRNA and protein levels, whereas those with induced FTH1 overexpression demonstrate a restoration of PYCR1 expression and a corresponding impact on tumor growth." (PMID 39294443, 2024). "Analysis of gene expression across multiple cancer types and their associations with cancer stage and patient survival in the TCGA-HNSC dataset identified a PYCR1 and MYO1B gene that could be a potential tumor-associated marker." (PMID 39768999, 2024). "In addition, mice daily treated with physiological levels of proline dramatically restored silencing of PYCR1-inhibited tumor growth." (PMID 37845207, 2023). "Moreover, the PYCR1 microarray contained 28 samples of ccRCC tissues and matched tumor edge renal tissues." (PMID 37340189, 2023). "Compared with that of WT rPYCR1, tumor growth was also notably attenuated by expression of rPYCR1 Y135F or rPYCR1 T238A, revealing the importance of Tyr-135 phosphorylation and enzymatic activity of PYCR1." (PMID 37777542, 2023). "Furthermore, NOD/SCID mice inoculated with spheroid cells showed that ablation of PYCR1 also inhibited tumor growth." (PMID 37845207, 2023). "Furthermore, we uncover that PYCR1/proline/cGMP-PKG axis mediates psychological stress-induced tumor growth and cancer stem-like traits." (PMID 37845207, 2023). "This was demonstrated in detail in breast cancer models, but PYCR1 and collagen upregulation co-occurs in many tumor types, suggesting that this mechanism might have a broader relevance." (PMID 36324182, 2022). "rtPCR analysis revealed no increase in Pycr1 mRNA expression in intestinal tissue harvested from mice three days or one week after depletion of the tumor suppressor Apc, but accumulation of the Pycr1 transcript and protein in intestinal tissue became evident two weeks post Apc depletion." (PMID 35130302, 2022). "Pyrroline-5-carboxylate reductase 1 (PYCR1) plays an important role in tumor development." (PMID 35371311, 2022). "Moreover, the inhibition of PYCR1 reduced tumor growth and invasion capabilities, simultaneously sensitizing cancer cells to chemotherapy with doxorubicin." (PMID 35454935, 2022). "Moreover, tumor development in the Lgr5-CreER/Apcfl/fl model depends on the activity of the transcription factor Myc and PYCR1 is a Myc target gene, suggesting that the enhanced expression of PYCR1 in CRC plausibly results from Myc transcriptional activity." (PMID 35130302, 2022). "In our NF and CAF models, however, we could not find consistent differences in glucose and glutamine usage, and targeting PYCR1 in CAFs resulted in reduced collagen in the stroma of tumour xenografts and in 2D and 3D cocultures with cancer cells." (PMID 35760868, 2022). "Furthermore, the effect of PYCR1 interference on tumor growth was evaluated in vivo through injecting tumor cells subcutaneously into nude mice." (PMID 35371311, 2022). "Moreover, the overexpression of PYCR1 significantly inhibited the tumor suppressor effect of hsa-miR-150-5p on NPC." (PMID 34696668, 2021). "Furthermore, the correlation between clinicopathological features and PYCR1 expression was investigated in 363 tumor samples." (PMID 34239351, 2021). "Indeed, forced expression of PYCR1 restored the propagation and invasion defects of FTO-depleted BLCA cells, indicating the essential tumor-promoting role of USP18/FTO/PYCR1 signaling network in BLCA." (PMID 33461172, 2021).